COL1A1 (collagen type I alpha 1 chain)
Diseases named in the same sentence as COL1A1 in open-access papers (continued):
Sharing a sentence is not in itself a finding about the gene and the disease.
breast carcinoma (continued). "The expression data of ECM fiber-encoding genes (e.g., COL1A1, COL1A2, FGA, FGB, FGG, ELN, FN1, and VTN) from 1358 patients with breast cancer were used for Kaplan–Meier overall survival analysis." (PMID 37369642, 2023). "For example, collagen type I alpha 1 (COL1A1) is abundant in the extracellular matrix of breast cancer cells, and knockdown of COL1A1 in cancer cell lines inhibits cancer cell migrations." (PMID 36732531, 2023). "In breast cancer cell lines, a positive correlation between COL1A1 and CXCR4 has been observed; specifically, knocking down COL1A1 reduced CXCR4 mRNA expression as compared to wild type cells." (PMID 37373151, 2023). "Breast cancer is associated with a dramatic downregulation of ADRP and FST along with upregulation of the Serpin, LOX-1, COL1A1, and MIF gene expressions, respectively." (PMID 35138531, 2023). "Clusters negative for EPCAM and KRT8, corresponded to the cells of the TME, like endothelial cells (CD31+), immune cells (CD45+) and fibroblasts (COL1A1+) and were present in all breast cancer subtypes." (PMID 36635273, 2023). "We found that compared with blank and negative control groups, COL1A1 expression and the secretion of exosomes by breast cancer cells were inhibited in the siRNA-COL1A1 group." (PMID 38045487, 2023). "We investigated the effects of collagen type I alpha 1 (COL1A1) on tumor-associated fibroblast activation and matrix remodeling in the tumor microenvironment of breast cancer." (PMID 38045487, 2023). "The expression of COL1A1 in breast cancer tissues serves as a valuable reference for assessing malignant progression and prognosis, as well as guiding targeted therapy in breast cancer patients." (PMID 38045487, 2023). "Links to COL1A1 mRNA were observed mainly in the context of fibrosis, but also lung adenocarcinoma and breast cancer." (PMID 37373151, 2023). "Genetic depletion of collagen VI (Col6a1) reduced the rate of tumour initiation and growth, while overexpression of collagen I (Col1a1) in breast cancer models has been shown to enhance tumour formation and progression and increase the incidence of metastasis." (PMID 35760868, 2022). "COL1A1 is upregulated in a lymph node environment, which coincides with findings in breast cancer, where collagen 1 fiber density was increased in lymph node metastasis, and lung cancer, where COL1A1 expression highly correlated with lymph node metastasis." (PMID 36741736, 2022). "Elevated expression of collagen type I alpha 1 chain (Col1a1) was found in mouse and human breast cancers." (PMID 36547361, 2022). "It has also been confirmed that COL1A1 can hasten the malignant phenotype and progression of various malignancies, such as gastric cancer, prostate carcinoma, mammary carcinoma, pancreatic ductal carcinoma, liver carcinoma, and lung carcinoma." (PMID 35530352, 2022). "Collagen factors COL1A1, COL1A2, and COL3A1 were often implicated in carcinogenesis or metastasis in a variety of tumor types, for instance breast cancer, gastric cancer, and cervical cancer." (PMID 36059672, 2022). "In breast cancer stroma, COL1A1 was identified as one of the most promising genes for tumor detection and treatment." (PMID 36013233, 2022). "In this regard, the knockdown of PSMG3 AS1 increased miR 143 3p expression, which mitigated the proliferation and migration capacity in breast carcinoma cells and reduced the mRNA and protein expression levels of COL1A1." (PMID 35846147, 2022). "For example, COL1A1, reported as an oncogene, promotes metastasis in breast cancer and colorectal cancer." (PMID 35832546, 2022). "Immunofluorescence detection of clinicopathological specimens also found that the immune infiltration level of M2-TAMs in breast cancer tissues with high COL11A1 expression was significantly higher than that in breast cancer tissues with low COL1A1 expression." (PMID 36160004, 2022).
breast carcinoma (continued). "Recently, it has been shown that a high level of COL1A1 is indicative of a more aggressive cellular behavior and poorer prognosis in patients with breast cancer, especially in those with ER+ breast cancer." (PMID 34475986, 2021). "PTK7 expression in breast cancer was significantly positively correlated with COL1A1, FN1, WNT5B, MMP11, MMP14 and SDC1 in breast cancer." (PMID 34367983, 2021). "RT‐qPCR and immunohistochemical staining characterized higher expression of COL1A1 mRNA and protein in breast cancer tissues than in adjacent normal tissues." (PMID 31957232, 2020). "COL1A1 is an ECM protein, whose overexpression was linked to breast cancer, gastric cancer, and colorectal cancers." (PMID 33542901, 2020). "This became evident from a study which reported that high levels of COL1A1 were associated with poor survival and a better response to cisplatin-based chemotherapy was observed in ER + breast cancer patients who had increased COL1A1 levels." (PMID 33167967, 2020). "The presence of the Col1A1/CHAD amplification event in the mouse model mirrors the 25% of human HER2 + ve breast cancers that also had amplification of a structurally conserved region." (PMID 31332182, 2019). "Acetylation of the COL1A1 gene promoter was facilitated by ROCK/Rho signaling pathways in breast cancer cells." (PMID 31521169, 2019). "First, we generated a score based on the average gene expression of PAPP-A/SNAI1/COL1A1 from a publicly available dataset of 327 patients with primary breast cancer (GSE20685)." (PMID 31046834, 2019). "Breast cancer cells downregulate miR-196b-5p, which decreases COL1A1 levels, to induce growth and metastasis." (PMID 31521169, 2019). "COL1A1 is overexpressed in a series of cancers including gastric cancer, breast cancer, cervical cancer, non-small lung cancer, and hepatocellular carcinoma." (PMID 30568862, 2018). "High expression levels of COL1A1 and FN1 were associated with high grade or advanced stage of breast cancer and poor prognosis." (PMID 30237810, 2018). "A high expression level of COL1A1 was observed in breast cancer with recurrence or a metastatic event after 1 year." (PMID 30237810, 2018). "In summary, breast cancer stroma-related genes, including JUN, FOS, ATF3, STAT1, COL1A1 and FN1, were all associated with tumor invasion and metastasis." (PMID 30237810, 2018). "As CAF induce higher collagen deposition to alter the extracellular matrix, and COX-2 inhibition diminishes α-SMA+ fibroblasts in PyMT/Col1a1 tumors, we characterized collagen levels in mammary tumors using Masson’s trichrome staining." (PMID 27000374, 2016). "We have shown that treatment with exogenous CS-E interfered with breast cancer cell motility through negative regulation of the expression of the pro-tumorigenic ECM molecule Col1a1." (PMID 25090092, 2014). "Lastly, we demonstrate that Col1a1 is a positively regulated target gene of the Wnt/beta-catenin pathway in breast cancer cells." (PMID 25090092, 2014). "We go on to show that CS-E negatively regulates Wnt/beta-catenin signaling, a known pro-tumorigenic pathway, and that Col1a1 is a positively regulated target gene of the Wnt/beta-catenin pathway in breast cancer cells." (PMID 25090092, 2014). "We further established that Col1a1 is a positively regulated target gene of the Wnt/beta-catenin pathway in breast cancer cells." (PMID 25090092, 2014). "COL1A1 has also been found induced in most breast carcinomas, and a subset of ovarian and colon carcinomas." (PMID 15836779, 2005). "Notably, FN1 and COL1A1, all regulated by TGFβ, exhibit coordinated expression in breast cancer lymph node metastases." (PMID 41231242, 2025). "Moreover, we further analyzed the expression of COL1A1 in primary breast cancer and metastatic lymph nodes of breast cancer and showed that COL1A1 was higher in metastatic lymph nodes than in primary breast cancer." (PMID 39157383, 2024).
breast carcinoma (continued). "In breast cancer cells, knockdown of COL1A1 limited the proliferation and invasion of cancer cells." (PMID 39845977, 2024). "The research in mouse models of breast cancer indicates that COL1A1 is a key extracellular matrix gene and is identified with copy number alterations through integrative in vitro and in vivo studies, while COL1A2 methylation is associated with ER/PR receptor status in breast cancer cohort." (PMID 38088228, 2024). "None of the other de novo SNVs (i.e., BCL11A, BCOR, and COL1A1) was recurrent in more than one sample nor has been linked to treatment failure in breast cancer, leaving the evolution of resistance unexplained in 12 of 13 replicates." (PMID 38527495, 2024). "Additionally, the upregulation of the COL1A1 and COL1A1 genes, among others, has been observed in breast cancers with brain metastases." (PMID 39273393, 2024). "Furthermore, the abnormal overexpression of COL1A1 in breast cancer was accompanied by increased TGF-β1 levels." (PMID 35138531, 2023). "Second, the specific cellular pathways underlying the effects of COL1A1 on breast cancer were not further investigated in this article." (PMID 38045487, 2023). "Interestingly, the expression profile of Ccl2, Col1a1, Col1a2, and Itgam was very close to most of the breast cancer samples, with a degree of variability among samples." (PMID 37243196, 2023). "Similarly, miR-328-3p was found to reduce COL1A1 mRNA levels in primary breast cancer cells, through binding to the mRNA 3′ untranslated region." (PMID 37373151, 2023). "In conclusion, we believe that SDC1 may be a potential target for blocking the interaction between COL1A1+ CAFs and tumor cells to promote immune infiltration in breast cancer." (PMID 37021816, 2023). "Collectively, our results suggested that COL1A1+ CAFs may be the main dangerous cells in the stromal microenvironment, which could promote tumorigenesis and lead to poor prognosis for breast cancer patients." (PMID 37021816, 2023). "We further explored whether high PYCR1 and COL1A1 expression correlated with clinical outcomes in patients with breast cancer." (PMID 35760868, 2022). "Finally, to address the question if metastatic outgrowth of breast cancer cells depends on the amount of trabecular bone, we took advantage of Col1a1-Krm2 mice, since these mice develop severe postnatal osteoporosis." (PMID 35158823, 2022). "When we further interrogated the expression of collagen genes commonly expressed in breast cancer ECM (COL1A1, COL1A2, COL3A1 and COL5A1) we observed decreased endogenous gene expression of these collagens in higher passage TU-BcX-4IC tumors compared to lower passage." (PMID 34370182, 2022). "We hereby observed remarkable differences in the number of osteoclasts, again independent of the Col1a1-Krm2 genotype, which essentially confirms previous data showing that breast cancer cells activate osteoclastogenesis to ultimately cause osteolytic lesions." (PMID 35158823, 2022). "In addition, protein–protein interaction network analysis confirmed that COL1A1 is a prognostic matrix gene in breast cancer, and its expression is related to the progression of breast cancer." (PMID 36131254, 2022). "In addition, a recent study demonstrated that COL1A1 participated in epithelial-to-mesenchymal transition (EMT) process in breast cancer." (PMID 33506107, 2021). "Co-expression analysis and gain- or loss-of-function of PTK7 in TNBC cell lines revealed that PTK7 participates in EGFR/Akt signaling regulation and associated with extracellular matrix organization and migration genes in breast cancer, including COL1A1, FN1, WNT5B, MMP11, MMP14 and SDC1." (PMID 34367983, 2021). "In addition, the high expression of COL1A1 in breast cancer was verified in the Pan‐Cancer Analysis Platform." (PMID 31957232, 2020). "Cellular expression of COL1A1 has been reported to possibly promote breast cancer metastasis." (PMID 33167967, 2020).
breast carcinoma (continued). "COL1A1 was significantly increased in breast cancer compared with normal breast tissue." (PMID 30237810, 2018). "So we anticipate that IGFBP5 could be a possible modifier on metastatic capacity of breast cancer through regulating COL1A1 or MMP11." (PMID 26569312, 2015). "Moreover, the negative regulation of Col1a1 gene expression by CS-E is necessary for its inhibitory effect on breast cancer cell motility." (PMID 25090092, 2014). "Together, our data demonstrate that CS-E could negatively regulate Col1a1 gene expression through inhibition of Wnt/beta-catenin signaling, which in turn led to decreased breast cancer cell motility." (PMID 25090092, 2014). "Here, we showed that expression of P4HA2 and collagen genes (Col1A1, Col3A1, and Col4A1) is significantly correlated during breast cancer development and progression, and that increased mRNA levels of P4HA2 are associated with poor prognosis in breast cancer patients." (PMID 24383403, 2014). "Therefore, targeting the interaction between COL1A1+ CAFs and tumor cells may be an effective treatment for breast cancer." (PMID 37021816, 2023). "In conclusion, the gene COL1A1 may potentially function as an oncogene in breast cancer." (PMID 38045487, 2023). "Additionally, COL1A1 knockdown suppressed the metastasis of breast cancer cells." (PMID 33506107, 2021). "Therefore, we hypothesized that the dysregulation of COL1A1 in breast cancer may be regulated by miR‐328‐3p." (PMID 31957232, 2020). "After the withdrawal of rapamycin treatment, mutated COL1A1 reinforced PI3K–AKT-mammalian target of rapamycin (mTOR) signals in cancer stem cells to sustain the metastatic burden of ERα-positive breast cancer cells; however, lung metastases were independent of mTOR signaling." (PMID 31521169, 2019). "Interestingly, while individual expression of each molecule does not predict for metastasis using KM Plotter analysis, the combination of high SEMA7A, COX-2, and COL1A1 mRNA expression results in significantly decreased distant metastasis free survival for breast cancer patients in this dataset." (PMID 30847405, 2019). "Thus, we show that Col1a1 is a positive regulator of breast cancer cell migration, and that inhibition of Col1a1 expression could mimic the effects of CS-E treatment." (PMID 25090092, 2014). "We found that COL1A1, MMP3, PDGFR and FZD7 were significantly increased/decreased in breast cancer brain metastasis compared with primary breast cancer, and the four genes were also acted as long-term outcome factors in breast cancer brain metastasis." (PMID 39157383, 2024). "MiR-133a has emerged as a tumor suppressor in non-small cell lung cancer (NSCLC), esophageal cancer (EC), prostate cancer (PC) and breast cancer (BC), targeting genes such as SOX4, EGFR, FSCN1, and COL1A1." (PMID 38504785, 2024). "The tumor microenvironment (TME) of HR+/HER2- breast cancer cells is composed of CD3D+ T cells, CD68+ macrophages, COL1A1+ fibroblasts, and FLT1+ endothelial cells." (PMID 38892065, 2024). "Together, our results suggested that COL1A1+ CAFs and Scissor+ tumor cells are harmful and can inhibit immune infiltration through SDC1 receptor interaction and lead to poor prognosis of breast cancer patients." (PMID 37021816, 2023). "We utilized a syngeneic mouse model of bone metastasis by using the EO771 breast cancer cell line in mice harboring a conditional deletion of MERTK and TYRO3 in osteoblasts (Col1a1-2,3kb-cre+Mertkflox/flox and Col1a1-2,3kb-cre+Tyro3flox/flox)." (PMID 38203403, 2023). "COL1A1, as a further essential component of the ECM, was also correlated with breast cancer progression and metastasis." (PMID 36013233, 2022). "LC-MALDI-MS/MS and MALDI-TOF MSI analyses showed the upregulation of COL1A1 and COL1A2 in invasive breast cancer and COL6A3 in almost all breast cancer samples." (PMID 36278695, 2022).
breast carcinoma (continued). "Next, we analyzed the correlation of compression-upregulated metabolic genes with compressive stress markers (COL1A1, COL3A1, HAS2, and HAS3 genes) and tumor size in breast cancer subtypes: luminal A (LumA), luminal B (LumB), Her2, and triple-negative (TN)." (PMID 31428701, 2019). "There is similar amplification event at 17q21.33, including COL1A1 and CHAD that occurs in 8% of breast cancer patients." (PMID 31332182, 2019). "Oncome analysis showed that the high expression levels of COL1A1 and FN1 correlated to an advanced stage of breast cancer and poor clinical outcomes." (PMID 30237810, 2018). "These high expression levels of COL1A1 and FN1 were correlated to late stage of breast cancer and poor clinical outcomes." (PMID 30237810, 2018). "Taken together, our results showed that at least COL1A1, ACTA2, and FAP were significantly upregulated on mRNA levels in CAS from canine mammary carcinoma similar to human mammary carcinoma samples, whereas CXCL12 is downregulated." (PMID 28531107, 2017). "Given that MMP2, COL1A1 and SPARC are all pro-metastatic genes, we suggest these genes play crucial roles in LOX+ breast cancer metastasis." (PMID 27147578, 2016). "Further functional and protein-protein interactions studies are needed to clarify a likely correlation between IGFBP5, COL1A1 and MMP11 considering the metastasis process in breast cancer." (PMID 26569312, 2015). "Together, these data established a Wnt/beta-catenin - collagen axis in breast cancer cells, and demonstrated that Wnt/beta-catenin pathway inhibition by either IWR-1 or CS-E interferes with Wnt3a-mediated induction of Col1a1 expression." (PMID 25090092, 2014). "COL1A1, COL1A2, COL11A1, and COL5A1 have been reported to regulate several cancers, including colorectal cancer, esophageal cancer, hepatocellular carcinoma, renal cell carcinoma, breast cancer, and gliomas." (PMID 38639039, 2024). "Reported that COL1A1 was significantly decreased in breast cancer brain metastasis, they did not explore the long-term impact of COL1A1 in breast cancer brain metastasis." (PMID 39157383, 2024). "The extracellular matrix (ECM) is a vital component of the tumor microenvironment and plays an important role in tumor invasion and metastasis, and COL1A1 was proven to be a pro-metastatic ECM gene, which is believed to be a poor long-term survival factor in breast cancer." (PMID 39157383, 2024). "Increased expression of COL1A1 and COL1A2 are considered to influence tumor invasion and progression and are reported in several types of cancer, such as gastric, colorectal, and breast cancer." (PMID 35159353, 2022). "Our previous analysis of open databases showed that ITGA11 expression was correlated positively with PDGFRB, ACTA2, TNC, COL1A1, and COL1A3 in human breast cancer, and the immunostainings showed that α11, PDGFRβ, and TNC were colocalized to CAF subsets in human breast cancer stroma." (PMID 36003785, 2022). "Knockdown of COL1A1 inhibited metastasis and EMT of breast cancer cells." (PMID 34399848, 2021). "The expression levels of E-cadherin, vimentin, DDR1, DDR2, α2 integrin, α11 integrin, COL1A1, MT1-MMP, BIK, estrogen receptor α, progesterone receptor, and HER2 mRNAs in 58 breast cancer cell lines were analyzed in silico, by using the Broad-Novartis Cancer Cell Line Encyclopedia (CCLE) database." (PMID 31130862, 2019). "Among the compression-upregulated metabolic genes, the expression of ENO2 gene was significantly and positively correlated with COL3A1 and HAS1 genes, whereas PFKFB3 genes were significantly and positively correlated with that of COL1A1, HAS2, and HAS3 genes in breast cancer patient tissues." (PMID 31428701, 2019). "To test this hypothesis, we investigated the correlation between a three-gene signature of PAPP-A, COL1A1, and SNAI1 and clinical outcomes in breast cancer patients." (PMID 31046834, 2019).